SENP1 (SUMO specific peptidase 1)
Diseases named in the same sentence as SENP1 in open-access papers (continued):
Sharing a sentence is not in itself a finding about the gene and the disease.
ovarian carcinoma (continued). "Thus, a higher level of SENP1 is highly correlated with worse ovarian cancer patient survival following platinum drug-based therapy." (PMID 33795649, 2021). "Thus, this study not only identifies a novel mechanism regulating JAK2 activity, but also provides with a potential approach to treat platinum-resistant ovarian cancer by targeting SENP1/JAK2 pathway." (PMID 33795649, 2021). "Furthermore, SENP1-mediated deSUMOylation and the activation of janus kinase 2 (JAK2) promotes platinum resistance in ovarian cancer, which can be overcome by pharmacological inhibition of SENP1 that sensitizes cancer cells to cisplatin." (PMID 34503213, 2021). "Thus, inhibition of SENP1 is a promising strategy for the treatment of platinum-resistant ovarian cancer." (PMID 33795649, 2021). "To explore the clinical application of anti-SENP1 for the treatment of platinum-resistant ovarian cancer patients, we found that SENP1 siRNA or inhibitor Momordin Ic exhibits remarkable synergistic effect with cisplatin on platinum-resistant ovarian cancer." (PMID 33795649, 2021). "To test whether SENP1 contributes to cisplatin-resistance in ovarian cancer cells, we depleted SENP1 by siRNA and found SENP1 depletion significantly increased the cell sensitivity to cisplatin in both SKOV3 CR and IGROV1 CR cells." (PMID 33795649, 2021). "Others reported that SENP1 affects cell survival, proliferation, and apoptosis in multiple myeloma, cell migration and invasion of neuroblastoma, and sensitivity of hypoxic ovarian cancer cell to cisplatin." (PMID 27741516, 2016). "Also, our data provide the possibility that by combing SENP1 inhibition with standard chemotherapy in ovarian cancer tumor resistance may be reduced." (PMID 26548925, 2015). "These assays found that SENP1 mRNA was highly upregulated, while SUMO3 level was decreased in platinum-resistant ovarian cancer cells (IGROV1 CR), suggesting a possible role of SENP1 in the regulation of platinum-resistance via SUMOylation in ovarian cancer." (PMID 33795649, 2021). "In this study, we identified that SENP1 positively regulated the expression of HIF-1α by deSUMOylation and weakened the sensitivity of hypoxic ovarian cancer cells to cisplatin." (PMID 26548925, 2015). "In this study, we mimicked a hypoxic model of ovarian cancer with CoCl2, investigated the effects of SENP1 on HIF-1α and the internal mechanisms, and detected the effects of SENP1 on ovarian cancer chemosensitivity." (PMID 26548925, 2015). "Significantly, this novel SENP1/JAK2 axis is activated in platinum-resistant ovarian cancer in a manner dependent on a transcription factor RUNX2 and activated RUNX2/SENP1/JAK2 is critical for platinum-resistance in ovarian cancer." (PMID 33795649, 2021). "There was a good correlation between SENP1 and phosphorylated JAK2 levels in these tested sensitive and resistant patient tumor samples, indicating SENP1 upregulation is correlated with JAK2-mediated platinum-resistance in ovarian cancer." (PMID 33795649, 2021). "The results may have important implications for the potential use of SENP1 regulation in HIF-1α inhibition and for improving chemosensitivity of ovarian cancer cells to cisplatin." (PMID 26548925, 2015). "Ectopic expression of JAK2 in IGROV1 CR cells with depleted SENP1 restored cisplatin resistance of IGROV1 CR cells to the similar levels as cells treated with control siGL2, suggesting that JAK2 is the primary target of SENP1 to promote platinum-resistance in ovarian cancer cells." (PMID 33795649, 2021).
colorectal cancer (8 papers, 2014 to 2026). A primary or metastatic malignant neoplasm that affects the colon or rectum. "SENP1 silence upregulates cyclin dependent kinase inhibitors such as p16, p19, p21 and p27, resulting in colorectal cancer cell cycle arrest." (PMID 38389923, 2024). "It was also observed that SENP1 was upregulated in colorectal cancer cell lines and clinical samples." (PMID 38389923, 2024). "In colorectal cancer, Mc induces cell cycle arrest and apoptosis through inhibiting SENP1-mediated c-Myc deSUMOylation." (PMID 38389923, 2024). "In this regard, we found that overexpressed MYB correlates positively with SENP1 expression in leukemia, breast, and colorectal cancer patients according to mining of data from TCGA." (PMID 37468105, 2023). "For instance, MCM3AP-AS1 can enhance cell growth and metastasis in colorectal cancer via modulating miR-193a-5p/SENP1." (PMID 33942704, 2021). "In addition, high expression of SENP1 was strongly related to poor prognosis in renal cell carcinoma, nasopharyngeal carcinoma and colorectal cancer." (PMID 38389923, 2024). "In colorectal cancer, SENP1 drives chemotherapy resistance through reducing RNF168 SUMOylation." (PMID 38389923, 2024). "Targeting SENP1 can significantly reduce irinotecan resistance in colorectal cancer patients." (PMID 38389923, 2024). "In colorectal cancer, microRNA-133α-3p targets SENP1 to block cell cycle (Zhou GQ." (PMID 38389923, 2024). "We therefore asked whether overexpressed MYB correlates with SENP1 expression in leukemia, breast, and colorectal cancer patients." (PMID 37468105, 2023). "Additionally, SENP1 facilitates the lung metastasis of colorectal cancer cells." (PMID 38389923, 2024). "In colorectal cancer (CRC), SENP1 contributes to drug resistance by stabilizing HIF-1α, thereby enhancing survival, migration, and metabolic adaptation under stress conditions." (PMID 39859203, 2025). "The deSUMOylation of ELOC induced by SENP1 promoted USP51 bind to ELOC and facilitated the deubiquitylation and stabilization of HIF-1α, consequently enhancing colorectal cancer cells stemness." (PMID 38389923, 2024). "In colorectal cancer, SENP1 inhibits RNF168 phase separation, which in turn promotes DNA damage repair and drug resistance in colorectal cancer." (PMID 37980165, 2023). "Given their significant role in cancer progression, particularly in colorectal cancer, which shares similarities with mEOC, we chose to further investigate KIN17 and SENP1 in the context of mEOC to better understand their contribution to this challenging cancer subtype." (PMID 39859203, 2025). "Since MYB is overexpressed in many cancers including leukemia, breast, and colorectal cancers, it may under these conditions be less SUMO-repressed according to the autoactivation hypothesis due to the deregulation of SENP1 expression." (PMID 37468105, 2023).
prostatic intraepithelial neoplasia (8 papers, 2012 to 2024). "SENP1 is overexpressed in prostatic intraepithelial neoplasia (PIN), a pre-cancerous prostatic lesion, and in PC tissue with respect to the normal ones." (PMID 35465332, 2022). "The study in mice demonstrated that prolonged SENP1 overexpression is critical for transforming the normal prostate gland, and gradually facilitates the onset of high-grade prostatic intraepithelial neoplasia." (PMID 33923236, 2021). "Moreover, the overexpression of SENP1 was reported in precancerous prostate intraepithelial neoplasia in humans, confirming that SENP1 plays a role in cancer transformation." (PMID 33923236, 2021). "In addition, their initial results in vivo in transgenic mice indicated that over-expression of SENP1 leads to the development of prostatic intraepithelial neoplasia (PIN) at an early age." (PMID 22666381, 2012). "The expression of SENP1 is frequently observed in PCa and precancerous prostatic intraepithelial neoplasia (PIN) tissues, and the overexpression of SENP1 correlates with increased aggressiveness and recurrence of PCa." (PMID 34503213, 2021). "However, mice expressing an androgen-responsive promoter driven SENP1-transgene (SENP1-Tg) develop high-grade prostatic intraepithelial neoplasia, but not carcinoma." (PMID 27852060, 2017).
glioblastoma (7 papers, 2021 to 2025). The most malignant astrocytic tumor (WHO grade IV). "The decrease in SENP1 expression elevates the apoptosis rate in human glioblastoma cells, while its deficiency inhibits the NF‐κB signalling pathway, resulting in apoptosis of tumour cells in multiple myeloma." (PMID 39205481, 2024). "In glioblastoma, the study observed that SENP1-mediated deSUMOylation of methyltransferase like 3 (METTL3) promoted MYC protein expression, thereby accelerating self-renewal of tumor cells." (PMID 38389923, 2024). "Knockdown of SENP1 can inhibit the phosphorylation of IκBα and Akt and inhibit the expression of Bcl-xL and cyclinD1, thereby promoting glioblastoma cell apoptosis." (PMID 33898460, 2021). "UBE2I, UBA2, PIAS3, and SENP1 were highly expressed in glioblastoma." (PMID 33898460, 2021). "Moreover, UBE2I, UBA2, PIAS3, and SENP1 were highly expressed in glioblastoma, whereas PIAS1, RANBP2, SENP5, and SENP2 were downregulated in glioblastoma." (PMID 33898460, 2021). "Also, SENP1 is able to be used as a prognostic biomarker for glioblastoma." (PMID 38389923, 2024). "For example, in glioblastoma (GBM), SUMO machinery components are upregulated, such as SUMO activating enzyme (SAE1), SUMO conjugating enzyme (Ubc9) and SUMO specific protease (SENP1), promoting tumor progression." (PMID 39211047, 2024). "As can be seen from the figure, UBE2I, UBA2, PIAS3, and SENP1 were upregulated in glioblastoma, whereas PIAS1, RANBP2, SENP5, and SENP2 were downregulated in glioblastoma." (PMID 33898460, 2021). "In glioblastoma CSCs, YY1 mediates self-renewal through regulation of the SENP1/METTL3/MYC axis." (PMID 37444616, 2023). "In glioblastoma (GBM), proteins involved in the SUMOylation cascade are upregulated, such as E1 (SAE1), E2 (UBC9) components, and SENP1, promoting tumor progression." (PMID 37415251, 2023). "YY1 transcriptionally upregulates sentrin/SUMO-specific protease 1 (SENP1) and enhances the methylase activity of methyltransferase-like 3 (METTL3), leading to increased N6-Methyladenosine (m6A)-modification levels in MYC mRNA, which promotes the self-renewal of glioblastoma stem cells (GSCs)." (PMID 37444616, 2023).
renal cell carcinoma (6 papers, 2016 to 2024). "In renal cell carcinoma cells, overexpressed SENP1 enhances the transcriptional activity of hypoxia-inducible factor 2α (HIF-2α) through deSUMOylation, resulting in stemness-related genes expression increasing." (PMID 38389923, 2024). "MicroRNA-186 overexpression directly downregulates SENP1 protein expression and inhibits cell proliferation in renal cell carcinoma." (PMID 38389923, 2024). "While an important role for the SUMO protease SENP1 is recognized in multiple solid cancers, its role in renal cell carcinoma (RCC) pathogenesis, particularly the most dominant subtype, clear cell RCC (ccRCC), is poorly understood." (PMID 36284084, 2022). "In addition, SENP1 could also promote renal cell carcinoma tumorigenesis." (PMID 33686713, 2021). "One report showed that SUMOylation-defective MITF germline mutation predisposes carriers to melanoma and renal carcinoma, but, so far, there is no report on a clear role of SENP1 in renal cell carcinoma." (PMID 27741516, 2016).
triple-negative breast carcinoma (6 papers, 2020 to 2023). An invasive breast carcinoma which is negative for expression of estrogen receptor (ER), progesterone receptor (PR), and human epidermal growth factor receptor 2 (HER2). "SENP1 is highly expressed in triple-negative breast cancer, which is associated with HER-2 loss." (PMID 34422639, 2021). "Sentrin-specific protease 1 (SENP1) can amplify invasion and lung metastasis of triple negative breast cancer cells." (PMID 35408841, 2022). "Furthermore, they found that SENP1 is essential for triple-negative breast cancer cell proliferation and migration in vitro, as well as for tumor formation and metastasis in vivo." (PMID 37468105, 2023). "SENP1 silencing also attenuated the growth and invasiveness of triple-negative breast cancer cells." (PMID 33371766, 2021).
glioma (5 papers, 2021 to 2025). A benign or malignant brain and spinal cord tumor that arises from glial cells (astrocytes, oligodendrocytes, ependymal cells). "SIRT1 plays a significant role in glioma development, and its activity is regulated by SENP1 (sentrin-specific protease 1)." (PMID 40710366, 2025). "Downregulation of SIRT1 reverses the inhibitory effects of SENP1 depletion on the malignant phenotype of glioma cells, indicating that SIRT1 is crucial for maintaining the malignant characteristics of glioma cells." (PMID 40710366, 2025). "It was previously demonstrated that the silencing of SENP1 inhibits the growth, migration, and survival of human glioma cells." (PMID 33371766, 2021). "Additionally, Liu’s work sheds light on the impact of SENP1-mediated de-SUMOylation of SIRT1 in glioma development." (PMID 38801243, 2024). "It has been reported that SENP1 is positively correlated with the malignant degree of glioma." (PMID 33951297, 2021). "In gliomas, SENP1 expression is positively correlated with tumor grade." (PMID 34422639, 2021).
neuroblastoma (5 papers, 2014 to 2023). Neuroblastoma (NB) is the most common solid, extracranial childhood tumor. "It was similarly reported that the Inhibition of SENP1 in neuroblastoma cells significantly suppressed their migration and invasion capacity." (PMID 33371766, 2021). "In addition, several studies have indicated that SENP1-mediated deSUMOylation is protective against oxidative stress in cardiomyocytes and neuroblastoma cells." (PMID 25411797, 2014).
brain ischemia (4 papers, 2016 to 2023). Diminished or absent blood supply to the brain caused by obstruction (thrombosis or embolism) of an artery resulting in neurologic damage. "SENP1 has been implicated in the development of ischemia, such as the increasing expression of SENP1 in neurons in response to brain ischemia." (PMID 32495523, 2020). "We first reported SENP1 in pericytes played a protective role in cerebral ischemia with Cspg4‐Cre; senp1f/f mice." (PMID 32495523, 2020). "In the present study, we investigate the potential role of SENP1 in pericytes in the brain ischemia." (PMID 32495523, 2020). "To investigate the role of SENP1 on cell apoptosis, we focus on the expression of the apoptosis‐related proteins, such as Fas‐L, bcl‐2, and cleaved caspase 3 during brain ischemia." (PMID 32495523, 2020). "Biochemical analysis and immunohistochemistry methods were used to address the role and mechanism of pericyte‐specific SENP1 in the pathological process of brain ischemia." (PMID 32495523, 2020). "This represents the first report on the use of neuron-specific deletion of SENP1 in a mouse stroke model to determine the consequences of hyper-SUMO conjugation on neuronal survival in response to cerebral ischemia." (PMID 27882949, 2016). "To evaluate the role of SENP1 in neuronal damage following brain ischemia and reperfusion (I/R), we first examined the expression of SENP1 in major brain areas of C57BL/6 mice, including cerebellum, cortex and hippocampus." (PMID 27882949, 2016). "Our results revealed a protective role of SENP1 in pericytes in cerebral ischemia in mice, which could become a new therapeutic strategy for brain ischemic stroke." (PMID 32495523, 2020). "Although we have focused on critical role of pericyte SENP1 signaling during brain ischemia, other events may be equally important in the modulation of pericyte function." (PMID 32495523, 2020). "Moreover, SENP1 protects neurons by inhibiting apoptosis during transient brain ischemia/reperfusion, consistently with our previous finding in myocardial IRI." (PMID 30419807, 2018). "However, little is known about SENP1 in pericytes in cerebral ischemia." (PMID 32495523, 2020). "It suggested us that pericyte‐derived SENP1 may play an important role in the cerebral ischemia." (PMID 32495523, 2020). "SENP1, a SUMO‐specific proteases 1, plays a protective role in pericytes after cerebral ischemia in mice." (PMID 32495523, 2020).
leukemia (4 papers, 2013 to 2025). A malignant (clonal) hematologic disorder, involving hematopoietic stem cells and characterized by the presence of primitive or atypical myeloid or lymphoid cells in the bone marrow and the blood. "In an identical experiment concerning recombinant full-length human SENP1 (rfSENP1) obtained from SENP1 total RNA derived from human basophilic leukemia KU-812 cells, the estimated inhibitory IC50 value for VA was 1.64 ± 0.23 μM." (PMID 41303693, 2025). "Moreover, we observed decrease and increase of SUMOylation of exogenous PKM2 by ectopically expressing sentrin/SUMO-specific protease 1 (SENP1), or SUMO1 in NB4 leukemia cell lines respectively, suggesting that PKM2 is a SUMOylated protein in leukemia cells." (PMID 33473116, 2021).
lymph node metastasis (4 papers, 2015 to 2022). "SENP1 expression was significantly linked to adverse tumor features including advanced stage, high Gleason grade, and presence of lymph node metastases, preoperative PSA levels, and early biochemical recurrence in our analysis." (PMID 26202067, 2015). "In addition, increased SENP1 mRNA expression was associated with histopathological subtype (p = 0.011), the occurrence of lymph node metastasis (p = 0.008), and higher TNM stage (p = 0.015)." (PMID 35782332, 2021). "Thus, SENP1 expression was associated with larger tumor size and occurrence of lymph node metastasis; and SENP1 expression was correlated with larger tumor size and lymph node metastasis, which were features of more advanced TNM stage." (PMID 35782332, 2021). "In this study, we observed that in patients with surgical NSCLC receiving adjuvant chemotherapy, SENP1 expression was correlated with larger tumor size, histopathological subtype, the occurrence of lymph node metastasis, and higher TNM stage." (PMID 35782332, 2021). "In addition, SENP1 expression was positively correlated with histologic grade (P = 0.045, χ2 = 6.918, r = 0.202) and lymph node metastasis (P = 0.023, χ2 = 9.564, r = 0.256) in TNBC specimens." (PMID 35342335, 2022).
multiple myeloma (4 papers, 2016 to 2024). "Similarly, SENP1 deletion inhibits NF-кB signaling pathway, resulting in tumor cell apoptosis in multiple myeloma." (PMID 38389923, 2024). "Previous studies showed that the inhibition of SENP1 could reduce cell proliferation and induce apoptosis of multiple myeloma cells through the modulation of NF-κB signalling." (PMID 33371766, 2021).
pancreatic cancer (4 papers, 2016 to 2024). "Previous studies have shown that the overexpression of SENP1 in pancreatic cancer is related to the pathological stage and vascular invasion of patients." (PMID 34422639, 2021). "In pancreatic cancer, the SENP1 marker is expressed at high level." (PMID 38389923, 2024). "Furthermore, knockdown of SENP1 by SENP1-siRNA inhibited pancreatic cancer cell proliferation, migration, and invasion, suggesting that SENP1 played an important role in PDAC progression and metastasis." (PMID 27178176, 2016). "The function of SENP1 in invasion and metastasis was also proved in several other cancers including TNBC and pancreatic cancer." (PMID 38389923, 2024). "In terms of the correlation of SENP1 with clinical features, a previous study shows that SENP1 expression positively correlates with lymph node metastasis and TNM stage in patients with pancreatic cancer." (PMID 35782332, 2021).
pancreatic ductal adenocarcinoma (4 papers, 2015 to 2021). An infiltrating adenocarcinoma that arises from the epithelial cells of the pancreas. "With respect to the SENP1 expression in cancer tissues and adjacent tissues, it is suggested that SENP1 upregulates in pancreatic ductal adenocarcinoma tissues than in adjacent tissues." (PMID 35782332, 2021). "Clinical data showed that SENP1 was positively associated with lymph node metastasis and TNM stage pancreatic ductal adenocarcinoma (PDAC)." (PMID 27178176, 2016). "They further showed that knockdown of SENP1 using siRNA inhibited the growth of pancreatic ductal adenocarcinoma." (PMID 25893082, 2015).